LIF (LIF interleukin 6 family cytokine)
Diseases named in the same sentence as LIF in open-access papers (continued):
Sharing a sentence is not in itself a finding about the gene and the disease.
chordoma (4 papers, 2020 to 2024). Chordomas are rare malignant tumors arising from embryonic remnants of the notochord in axial skeleton. "Previous studies suggested that some cytokines and chemokines, including TNFα, LIF, IL-6 and IL-8 played important roles in the immune microenvironment of chordoma, but relatively few studies had been conducted." (PMID 38983929, 2024). "stained some kinds of cytokines in 14 chordoma tissues and found that the expression level of TNFα in chordoma was negatively correlated with the survival time of patients, and positively correlated with higher LIF and PD-L1expression in chordoma." (PMID 38983929, 2024). "LIF has been found to be a promoter of CSCs in chordoma cell lines, with upregulation of NANOG, Oct4, and Klf4." (PMID 35204717, 2022). "Increased LIF can also increase invasion and migration of chordoma cell lines, through decreases in E-cadherin and CK19 and increases in ZEB2 and MET." (PMID 35204717, 2022). "Experiments with chordoma cell lines have shown that LIF can induce chemoresistance by increasing expression of the ABCG2 drug transporter." (PMID 35204717, 2022). "Exposure of chordomas to TNF-α upregulates not only its own gene expression but also LIF expression, and vice versa; both cytokines are correlated with increased tumor size, implicating these factors in chordoma growth." (PMID 32733369, 2020). "Expression of either TNF-α or LIF in chordoma cell lines promoted cell migration, invasive capabilities, and anchorage-independent growth, demonstrating their pro-tumoral and metastatic potential." (PMID 32733369, 2020). "Recently, it had been discovered that kinds of cytokines and chemokines, such as TGFβ, TNFα, CCL5, IL-8, IL-6 and LIF, also as important mediators of cellular interactions, had been found to be highly expressed in chordomas and play important roles in the immune microenvironment." (PMID 38983929, 2024). "Leukemia inhibitory factor (LIF) is a cytokine in the interleukin-6 family whose functions include regulating proliferation of cancer stem cells, like those often found in chordoma." (PMID 32733369, 2020).
depression (4 papers, 2022 to 2025). "In addition, Yes-related proteins can affect astrocyte maturation and differentiation by regulating endothelial LIF secretion, which has been shown to be closely associated with episodes of major depression." (PMID 36496703, 2022). "The increase in a LIF expression mediated by EF-2001 affected the levels of the myelin proteins such as MBP (myelin-based protein) and MAG (myelin-associated glycoprotein) and alleviated the depression symptoms by the enhancement of the NF-κB p65/LIF/STAT3 pathway." (PMID 38397099, 2024). "Conversely, in males, inflammation was inversely associated with depression severity, with protective effects from regulatory mediators (IL-2, IL-4, IL-6, IL-15, LIF, TNF-α, β-NGF) against depression." (PMID 40305313, 2025).
esophageal adenocarcinoma (4 papers, 2022 to 2024). A malignant tumor with glandular differentiation arising predominantly from Barrett mucosa in the lower third of the esophagus. "Within esophageal adenocarcinoma ex vivo biopsies, higher tumor cell LIF secretion was significantly negatively correlated with infiltration by lymphocytes." (PMID 35204717, 2022). "Serum LIF levels of esophageal adenocarcinoma patients were significantly elevated in patients who would go on to have poor pathological response to treatment." (PMID 35204717, 2022). "Studies of esophageal adenocarcinoma cell lines and ex vivo patient tumor biopsies found that LIF was significantly upregulated in terms of secretion and intracellular expression of radioresistant cells, and radiation treatment further increases LIF secretion by cancer cells." (PMID 35204717, 2022).
ischemia (4 papers, 2017 to 2025). A hypoperfusion of the BLOOD through an organ or tissue caused by a PATHOLOGIC CONSTRICTION or obstruction of its BLOOD VESSELS, or an absence of BLOOD CIRCULATION. "A key area of focus in this study examined the effect of LIF on mitochondrial function in striatum and prefrontal cortex brain regions affected by ischemia in aged male and female rat models." (PMID 40427631, 2025). "Recently, we showed that LIF decreases infarct volume, improves functional recovery, and upregulates Prdx4 in oligodendrocytes after ischemia." (PMID 26746670, 2017). "LIF has been shown to be protective to the myocardium under various stressors such as ischemia, indicating it could be a therapeutic target in various heart diseases." (PMID 37428809, 2023). "A similar concentration response experiment was performed to determine whether this concentration of LIF confers neuroprotection against in vitro ischemia." (PMID 26746670, 2017). "This suggests that the protective effects of LIF in males may be stronger in subcortical regions like the striatum, or that this region specificity could be related to the pathophysiological progression of ischemia." (PMID 40427631, 2025). "The LIF/LIFR signaling pathway plays a crucial role in myocardial protection, particularly under stress conditions such as ischemia or hemodynamic overload." (PMID 39726944, 2024). "Leukemia inhibitory factor (LIF) has been shown to protect both oligodendrocytes and neurons from ischemia by upregulating endogenous anti-oxidants, though the effect of ischemia and the protective role of LIF treatment in mitochondrial function have not been studied." (PMID 40427631, 2025). "Immunohistochemical detection of LIFR in neurons incubated under normoxia showed that LIF could hypothetically trigger protective signaling in the absence of ischemia." (PMID 26746670, 2017).
ischemic stroke (4 papers, 2017 to 2025). A stroke disorder caused by obstruction of blood flow to the brain, due to thrombotic (local blood clot formation) or embolic (due to a blood clot or other material traveling from another site) event. "Recognizing the critical role of mitochondrial dysfunction in assessing neuroprotective therapies after ischemic stroke, it is instrumental to find out how LIF alters the metabolic regulation in a tissue-specific manner." (PMID 40427631, 2025). "Receiver Operating Characteristic (ROC) analysis showed that salivary basic FGF, HGF, IL-3 and LIF can distinguish ischemic stroke patients from the control group with high sensitivity and specificity." (PMID 40221607, 2025). "In this study, we demonstrated that the concentrations of basic FGF, HGF, IL-3, and LIF most effectively differentiate ischemic stroke patients from the control group (AUC = 1, sensitivity and specificity = 100%)." (PMID 40221607, 2025). "Nevertheless, the ability to induce protective antioxidant enzymes makes LIF a promising treatment that will protect neural cells against immediate and delayed damage following ischemic stroke." (PMID 26746670, 2017). "In our study, LIF levels in saliva were significantly higher in patients with ischemic stroke." (PMID 40221607, 2025). "LIF was up regulated at D1 (with the log2Fold change at D1, D3, D7, D14, D21: 5.1705, 1.9495, 2.2962, 2.0899, 1.9872) and then gradually decreased with the progression of ischemic stroke." (PMID 29896414, 2018). "It was reported that LIF could protect neurons by upregulating the superoxide dismutase 3 after ischemic stroke." (PMID 29896414, 2018). "This may imply a role of LIF in the early period after ischemic stroke." (PMID 29896414, 2018). "In our study, the concentration of chemotactic factors (CTACK, IL-8, MIG, MIF) and growth factors (basic FGF, G-CSF, HGF, LIF, VEGF) was significantly higher in the unstimulated saliva of patients with ischemic stroke compared to the control group." (PMID 40221607, 2025). "However, the role of LIF in targeting mitochondrial dysfunction to impart neuroprotection from ischemic stroke injury has not yet been studied." (PMID 40427631, 2025).
liver cancer (4 papers, 2017 to 2024). An epithelial or non-epithelial malignant neoplasm that arises from the liver. "SM can down-regulate the abnormally elevated oncogene LIF in liver cancer tissue and be used to treat liver cancer by inducing autophagy and apoptosis through the LIF/miR192-5p/CyR61/Akt axis." (PMID 36278230, 2022). "For example, solamargine, a Solanum incanum herb-derived natural product, promotes antiproliferative effects, apoptosis, and autophagy in liver cancer cells by downregulating leukemia inhibitory factor (LIF), cysteine-rich angiogenic inducer 61 (CYR61), and AKT and upregulating miR-192-5p." (PMID 36835100, 2023). "Our results showed that Raloxifene inhibited STAT3 phosphorylation induced by IL-6, but not by LIF in Hep-3B liver cancer cells." (PMID 28430601, 2017).
muscular dystrophy (4 papers, 2014 to 2022). Muscular dystrophy (MD) refers to a group of more than 30 genetic diseases characterized by progressive weakness and degeneration of the skeletal muscles that control movement. "It was also stated that LIF has the potential to treat muscular diseases such as muscular dystrophy due to increased myoblast survival." (PMID 35250869, 2022). "In addition, LIF transgenic leukocytes can reduce fibrosis and play a potential therapeutic role in improving muscular dystrophy and sarcopenic obesity." (PMID 35250869, 2022). "Our analyses of CD11b/LIF transgenic mdx mice showed that the transgene reduces muscle inflammation and fibrosis, thereby validating the transgene as a therapeutic molecule for muscular dystrophy." (PMID 31243277, 2019). "In fact, in a study done with a mouse model of muscular dystrophy (MDX), the authors showed that exercise does increase the expression of LIF, but this does not happen in wild-type mice, highlighting the importance of this mechanism after dystrophic or injury events." (PMID 32012727, 2020).
myositis (4 papers, 2022 to 2025). "For instance, higher baseline levels of IL-12p70 and leukemia inhibitory factor (LIF) are associated with myositis, granulocyte-macrophage colony-stimulating factor is linked to rash, and interferon-gamma (IFN-γ) is relevant to various irAEs." (PMID 38183211, 2024). "Increased IL-1α, IL-21, LIF, and PlGF-1 levels were significantly associated with the incidence of myositis, and the serum levels of six cytokines (BTLA, GM-CSF, IL-4, PD-1, PD-L1 and TIM-3) were higher in patients who developed a rash." (PMID 36159840, 2022). "In a retrospective study of 51 patients with metastatic GI cancer, 17 of whom had GC, elevated LIF levels correlated with myositis; affected patients exhibited a median LIF concentration of 21.39 pg/mL compared to 12.72 pg/mL in those without myositis." (PMID 41163398, 2025). "Increased IL-1α, IL-21, LIF, and PIGF-1 levels were significantly associated with myositis incidence, while the serum levels of six cytokines (BTLA, GM-CSF, IL-4, PD-1, PD-L1 and TIM-3) were higher in patients with rash." (PMID 36159840, 2022).
neuroblastoma (4 papers, 2009 to 2024). Neuroblastoma (NB) is the most common solid, extracranial childhood tumor. "It is interesting to note that in concert with LIF, Bmp4 suppresses differentiation of the neural lineage in mESCs maintained under serum-free conditions supplemented with N2 and B27, which were originally developed to culture a neuroblastoma cell line and hippocampal neurons, respectively." (PMID 21731714, 2011). "Cytokines selected from primary, secondary, and tertiary clusters with respect to EPO (IL-11, KITLG, LIF, THPO) were chosen as experimental candidates, to test their effect on Egr2 mRNA expression in serum-starved EPOR-B104 neuroblastoma cells exactly." (PMID 24672526, 2014).
osteoarthritis (4 papers, 2022 to 2024). A noninflammatory degenerative joint disease occurring chiefly in older persons, characterized by degeneration of the articular cartilage, hypertrophy of bone at the margins and changes in the synovial membrane. "Interleukin (IL)-1β, tumor necrosis factor (TNF)-α, and IL-6 seem to be the main proinflammatory cytokines involved in the pathophysiology of osteoarthritis, even though others, including IL-15, IL-18, IL-21, leukemia inhibitory factor (LIF), and chemokines are implicated." (PMID 36850304, 2023). "The application of ALN to inhibit osteoclasts weakened the promotion of LIF on the early abnormal bone remodeling of OA and attenuated osteoarthritis." (PMID 35078447, 2022). "Moreover, LIF is produced by joint tissue cells and is overexpressed in osteoarthritis (OA), playing an important role in its pathogenesis." (PMID 38247858, 2024). "IL-6, Oncostatin-M (OSM), leukemia inhibitory factor (LIF), and other IL-6 family members promote osteoarthritis, either as inflammatory factors or by directly regulating matrix destruction." (PMID 35496642, 2022).
peripheral nerve injury (4 papers, 2014 to 2021). Injury to a peripheral nerve. "We chose three IL-6-type cytokines IL-6, CNTF, and LIF because these three factors are known as “injury factors” that are induced after peripheral nerve injury and have been studied regarding their effects on CNS regeneration." (PMID 25162623, 2014). "As LIF expression is up regulated after peripheral nerve injury, observed down regulation of LIFR for at least 2 weeks may prevent non-neuronal cells from undesired consumption of LIF." (PMID 31139050, 2019). "This, from the aspect of RNA expression, further supported that miR-494-3p, let-7e-5p, let-7a-5p, and let-7d-5p might regulate LIF and HMOX1 after peripheral nerve injury." (PMID 30558654, 2018).
autism (3 papers, 2013 to 2015). Persistent deficits in social interaction and communication and interaction as well as a markedly restricted repertoire of activity and interest as well as repetitive patterns of behavior. "The serum levels of CNTF were found to be lower and the levels of FGF-2 and LIF were found to be higher in children with autism compared to age-matched healthy controls." (PMID 25769033, 2015). "Previous clinical research reported that LIF gene was associated with schizophrenia, this present work may provide a new insight the relationship between MIA and schizophrenia as well as autism in terms of fetal brain development." (PMID 26043040, 2015). "Whether excess sAPPα may potentially be impacting gliosis and abnormal brain development through upregulation of gp130 and consequently gp130-related pathways such as Notch1 and LIF in some individuals with autism remains to be determined." (PMID 23840007, 2013). "Conversely, the levels of pro-BDNF, FGF-2, and LIF were found to be increased in autism sera compared to control (pro-BDNF, Student’s t-test, p = 0.0043; LIF, Student’s t-test, p = 0.0216; FGF-2, Student’s t-test, p = 0.0194)." (PMID 25769033, 2015).
bacterial pneumonia (3 papers, 2014 to 2024). Acute infection of the lung parenchyma caused by bacteria (e.g., Streptococcus pneumoniae, Haemophilus influenzae, Chlamydia pneumoniae, Mycoplasma pneumoniae, and Legionella pneumophila). "Among these cytokines, LIF as a pleiotropic cytokine, can substantially facilitate tissue protection during bacterial pneumonia, which is involved in tissue homeostasis." (PMID 38041547, 2024). "Administration of recombinant LIF to the airways has a protective effect in response to LPS treatment, hyperoxia and to bacterial pneumonia." (PMID 25277705, 2014). "Enhanced Fas, Fap, Il24, and Tnfsf15 expression is observed following LIF depletion in animals with bacterial pneumonia, which could contribute to the increased apoptosis observed here." (PMID 25277705, 2014).
brain injury (3 papers, 2020 to 2023). Acute and chronic (see also brain INJURIES, CHRONIC) injuries to the brain, including the cerebral hemispheres, CEREBELLUM, and brain STEM. "Recent studies have shown that in human myogenic cells, LIF can increase the number of myogenic cells by increasing mitosis and decreasing apoptosis and that LIF has neurodegenerative and protective functions in perinatal hypoxic-ischemic brain injury and has some pro-angiogenic potential." (PMID 35070509, 2022).
cervical cancer (3 papers, 2011 to 2022). A primary or metastatic malignant neoplasm involving the cervix. "However, high levels of LIF in cervical cancer tissue have also been associated with decreased patient survival." (PMID 35204717, 2022). "The Human Protein Atlas dataset shows that high expression of LIF is a poor prognostic marker for human cervical cancer, for which HPV and Ct are well-known risk factors." (PMID 36329823, 2022). "LIF inhibits the proliferation of cervical carcinoma cells through downregulation of HPV-16 oncogene expression." (PMID 35204717, 2022). "LIF-treated cervical cancer cells showed significantly reduced HPV LCR activation, reduced levels of E6 and E7 mRNA, and reduced proliferation." (PMID 21747640, 2011). "We report the novel use of LIF to inhibit viral oncogene expression in cervical cancer cells, with concomitant reduction in proliferation suggesting re-engagement of cell-cycle regulation." (PMID 21747640, 2011). "While HPV promotes cervical cancer via oncogenic transformation, Ct may promote cervical cancer and ovarian cancer via aberrant LIF signaling, which has been shown to regulate multiple hallmarks of cancer, including proliferation, metastasis and chemoresistance." (PMID 36329823, 2022). "LIF represses viral gene expression of HPV-16, thereby decreasing cervical carcinoma cell proliferation." (PMID 35204717, 2022). "SiHa cervical cancer cells were transfected with an HPV-16 promoter reporter construct and treated with leukemia inhibitory factor (LIF), a human cytokine of the interleukin 6 superfamily." (PMID 21747640, 2011). "As a phase I-tested pharmaceutical with little toxicity, LIF is a promising candidate for the treatment of CIN, cervical carcinoma, and other HPV-dependent pathologies, either independently or in combination with cytotoxic chemotherapy." (PMID 21747640, 2011).
cholangiocarcinoma (3 papers, 2015 to 2022). A carcinoma that arises from the intrahepatic biliary tree (intrahepatic cholangiocarcinoma) or from the junction, or adjacent to the junction, of the right and left hepatic ducts (hilar cholangiocarcinoma). "For example, in cholangiocarcinoma, LIF was found to regulate carcinogenesis and metastasis through the LIF/miR-181c pathway." (PMID 35654787, 2022). "To investigate the role of LIF in cholangiocarcinoma, we evaluated the expression of LIF and its receptor (LIFR) in human samples." (PMID 26296968, 2015). "In conclusion, autocrine and paracrine LIF signaling promote chemoresistance in cholangiocarcinoma by up-regulating Mcl-1 via a novel STAT3- and MAPK-independent, PI3K/AKT-dependent pathway." (PMID 26296968, 2015). "In cholangiocarcinoma cells, we tested LIF effects on proliferation, invasion, stem cell-like phenotype, chemotherapy-induced apoptosis (gemcitabine+cisplatin), expression levels of pro-apoptotic (Bax) and anti-apoptotic (Mcl-1) proteins, with/without PI3K inhibition, and of pSTAT3, pERK1/2, pAKT." (PMID 26296968, 2015). "LIF secretion and LIFR expression were assessed in established and primary human cholangiocarcinoma cell lines." (PMID 26296968, 2015).
Cognitive impairment (3 papers, 2016 to 2025). Abnormal cognition is characterized by deficits in thinking, reasoning, or remembering. "We show that TRPA1 deficiency accelerates BCAS-induced cognitive impairment and white matter injury and that the increase of leukemia inhibitory factor (LIF) through TRPA1 stimulation in astrocytes plays a protective role in CCH-induced VCI." (PMID 37478173, 2023). "Consistent with the results of cognitive impairment, myelin density was also decreased in LIF-neutralizing antibody-administered BCAS-operated mice compared with control antibody–administered mice." (PMID 37478173, 2023). "In conclusion, TRPA1 plays a protective role in CCH-induced cognitive impairment and white matter injury by activating astrocytes, increasing LIF production, and promoting OPC myelination." (PMID 37478173, 2023).